CGAS (cyclic GMP-AMP synthase)
Diseases named in the same sentence as CGAS in open-access papers (continued):
Sharing a sentence is not in itself a finding about the gene and the disease.
tumor (continued). "The combined system achieved the enhanced tumor synergistic immunotherapy through TME reprogramming via the peroxidase-like activity of the CoNCDs and cGAS–STING signaling pathway agonist synergistically." (PMID 37762239, 2023). "TDNs and Mn2+ have synergistic effects in triggering cGAS-STING activation, production of Ifnb/Isgs, M1 polarization and antigen presentation, providing a new anti-tumor immunotherapy strategy based on STING mediated TAM reprogramming." (PMID 37153576, 2023). "The downregulation of cGAS and STING genes through epigenetic modification is a shared characteristic among various tumor cells." (PMID 37920470, 2023). "Mechanistically, SLC14A1-positive CAFs promoted tumor stemness via the WNT5A/β-catenin pathway, and the cGAS-STING pathway maintained this particular phenotype." (PMID 37784082, 2023). "In the process, the cGAS pathway in astrocytes was activated with IFN-α and TNF-α activation, contributing to a tumor growth advantage." (PMID 37834184, 2023). "In vitro, IR780-ZnS@HSA activated the cGAS–STING pathway and induced ICD and pyroptosis in tumor cells." (PMID 37342347, 2023). "The cGAS/STING DNA sensing pathway is a critical upstream mediator of type I interferon production and is an important regulator of anti-tumor immunity." (PMID 36394642, 2023). "The B16 model maintains intact cGAS/STING and MDA5/MAVS signaling pathways, like other commonly used transplantable syngeneic tumor models." (PMID 36918588, 2023). "Here, viral DNAs in the cytosol activated cGAS and downstream activated STING, IRF3, IRF7, IFN gene expression, and tumor death through the generation of antitumor CD8+ and CD4+ effectors in murine models." (PMID 38139802, 2023). "Across different tumor types in TCGA database, a positive correlation between cGAS and STING RNA expression was found only in CSG-3 tumors with a high cGAS–STING functional activation signature." (PMID 37444620, 2023). "Nevertheless, we show that POLQ knockdown results in cGAS-STING activation and plays a complex role in the immune response that results in decreased tumor growth." (PMID 36976649, 2023). "TREX1 counteracts potential cGAS-STING induction in the TME and thereby the anti-tumor immune response by degrading tumor-derived DNA that is either spontaneously generated or induced by DNA damaging therapeutic approaches." (PMID 38022587, 2023). "Further, we uncover that cGAS and DNA‐PK cooperate for optimal STING‐dependent signaling, thereby defining tumor immunogenicity." (PMID 36574362, 2023). "The new findings raise the possibility that, in BAK1-competent tumor cells, pharmacological BCL-2- associated X (BAX, apoptosis regulator) inhibitors may accelerate MOM permeabilization-driven mtDNA release, inducing cGAS signaling prior to caspase-dependent cleavage and inactivation of cGAS." (PMID 37175888, 2023). "Large amounts of Mn2+ and Zn2+ would help to enhance cGAS/STING signal transduction and generate a large amount of ROS to damage mitochondria and induce tumor cell death." (PMID 37532731, 2023). "Under hypoxic conditions, cGAS-STING signaling decreases simultaneously with the release of mitochondrial DNA, both leading to muted anti-tumor responses, further evidencing the necessary role of STING signaling for anti-tumorigenesis." (PMID 37761934, 2023). "Radiotherapy (RT) induces micronuclei in tumor cells to activate cytoplasmic nucleic acid sensors, further activating the cyclic GMP-AMP synthase-stimulator of interferon genes (cGAS-STING) pathway and the expression of type I interferon (IFN-I)." (PMID 37833255, 2023). "cGAS/STING/IRF3 pathway is known to play a critical role in innate immune response and anti-tumor immunity." (PMID 38057852, 2023). "Collectively, these routes help transmit cGAS–STING signal mediators, such as cGAMP and dsDNA, from chromosomally unstable tumour cells to neighbouring bystander cells via direct cell–cell contacts or across the extracellular space to more distant cells." (PMID 36876871, 2023).
tumor (continued). "It will be interesting to understand the factors controlling IRF8 expression in TAMs and its function (cGAS/STING signaling activation and antigen presentation) for tumor immunotherapies to adjunct currently available ICIs." (PMID 37380989, 2023). "In the case of cancer therapy, cancer immunotherapy targeting the cGAS–STING pathway depends on multiple factors, such as the immune state, the magnitude of the cGAS–STING pathway, different cancer cell types, and tumor stages." (PMID 37686127, 2023). "In vitro application of the CHK1 inhibitor prexasertib to SCLC cells revealed an increase in cytosolic DNA and activation of the cGAS-STING-TBK1 signaling pathway, a significant increase in PD-L1 expression, and suppression of tumor immune escape." (PMID 37305685, 2023). "This underscores the importance of epigenetic modifications in the cGAS-STING pathway, tumor immune evasion, and the development of tolerance to T cell immunotherapy." (PMID 37920470, 2023). "Activation of the cGAS/STING innate immunity pathway is essential and effective for anti-tumor immunotherapy." (PMID 37193698, 2023). "IHC staining further showed increased protein levels of TET2, cGAS, STING and TBK1 in TET2-overexpressing tumours, in which the protein levels of STING and TBK1 were clearly decreased by RU.521 treatment." (PMID 37667220, 2023). "In this mini-review we will explore how cGAS–STING signalling in different cells in the TME can promote both anti-tumour and pro-tumour responses." (PMID 37534795, 2023). "The activation of the cGAS–STING pathway in cancer cells combines innate and adaptive immunity, regulates the tumor microenvironment, and can transform cold tumors into hot tumors, increasing the tumor’s sensitivity to immunotherapy." (PMID 36980689, 2023). "This review explores the self-regulatory mechanism of the cGAS-STING signaling pathway and expounds on its role in tumor immunotherapy, considering DNA sensing (cGAS senses dsDNA), the intracellular signaling cascade, and immune response activation." (PMID 37920470, 2023). "cGAS-STING pathway connects the cytotoxic effect and immune response into a new tumor treatment model." (PMID 37920470, 2023). "cGAS-STING signaling pathway has become a key innate immune pathway, promoting different immune responses and affecting tumor progression and metastasis." (PMID 37061706, 2023). "RA specifically bound to TDP‐43 and induced its mitochondria localization and mtDNA release, leading to cGAS/STING‐dependent activation of NF‐κB and type I IFN signaling, thereby reprogrammed TME and sensitized tumor response to anti‐PD1 antibody treatment." (PMID 36876644, 2023). "Increased cGAS-STING expression would promote increased activation of inflammatory genes leading to increased immune response and targeting the tumor for destruction." (PMID 36900195, 2023). "IFN-I expression can be induced by activating the cGAS-STING pathway, which induced tumor regression in breast, colon cancer and melanoma mouse models when STING agonists were administered." (PMID 36882786, 2023). "Our above data demonstrated that the Arf1‐ablated tumor cells induced activation of the NF‐κB, NLRP3 inflammasome, and cGAS‐STING triple pathways in DCs." (PMID 37786300, 2023). "Initially employed as a tumour vascular disruptor for anti-cancer treatment, DMXAA was later found to activate the cGAS-STING signalling in mouse models." (PMID 37448962, 2023). "A growing preclinical study has demonstrated that the cGAS-STING pathway plays pivotal roles in DC-mediated antigen cross-presentation and subsequent priming of tumor-specific CD8+ T cells." (PMID 37153627, 2023). "Suppression of cGAS-STING signaling downregulates apoptotic and senescence pathways, increasing the protection of malignant cells from host tumor surveillance." (PMID 37761934, 2023).
tumor (continued). "PARP inhibitors also have the capacity to activate the cGAS-STING pathway in immune cells, thereby inducing anti-tumor immunity by effectively exterminating cancer cells and promoting the release of tumor-derived DNA." (PMID 37920470, 2023). "Simultaneously, Mn2+ activated the cGAS-STING pathway to produce type I interferon and enhance tumor ICD." (PMID 37766117, 2023). "Tumor MPs (T-MPs) released from the tumor or cancer cells stimulate cGAS/STING and TBK1-STAT6 signaling pathways in TIME macrophages to reprogram them to immunosuppressive tumor-supportive M2 macrophages." (PMID 37380989, 2023). "Blocking the cGAS-STING pathway inhibited inflammatory response and reduced tissue damage, while activating the cGAS-STING pathway promoted antiviral and anti-tumor effects." (PMID 37667279, 2023). "This review summarizes the current research on the roles of cGAS, STING, and AIM2 in immune cells and tumor cells in the tumor microenvironment and discusses the future prospects of anti-tumor treatment approaches based on these molecules." (PMID 37046775, 2023). "The activation of the cGAS-STING pathway can also trigger downstream NF-κB signaling, which plays a significant role in regulating tumor growth." (PMID 38203626, 2023). "Here the authors report a role for the deubiquitinating enzyme TRABID in regulating mitotic cell division and suppressing anti-tumor immunity, suggesting that TRABID inhibition induces micronuclei and activates cGAS/STING pathway." (PMID 37237031, 2023). "Mechanistically, Fusobacterium nucleatum-derived succinic acid inhibits the cGAS-interferon-b pathway, limiting the trafficking of CD8+ T cells to the tumor microenvironment (TME) in vivo and inhibiting anti-tumor responses." (PMID 38169837, 2023). "Activating the cGAS-STING pathway can regulate intrinsic cellular programs, such as inducing autophagy in tumor cells." (PMID 36936940, 2023). "Our experimental and clinical results suggest that cGAS-STING signaling-derived IFN-Is promote chemotherapeutic efficacy, but strategies to avoid the tumor-promoting disadvantages this pathway remain a challenge." (PMID 37670034, 2023). "Hence, inducing tumor cell senescence or death (increasing IRF8 expression or radiotherapy) may increase the signal strength of cGAS/STING signaling in TIME MICs (macrophages and DCs) by phagocytosing the cytosolic dsDNA to create a proinflammatory and cytotoxic TIME." (PMID 37380989, 2023). "Both tumor cells and myeloid cells express cGAS and STING, but accumulating evidence suggests that, in the tumor microenvironment, cGAMP is primarily produced by tumor cells, due to the presence of cytoplasmic dsDNA." (PMID 36757811, 2023). "A relatively new strategy of repolarizing TAMs involves the cyclic guanosine monophosphate-adenosine monophosphate synthase (cGAS)-stimulated interferon gene (STING) pathway, which appears to be sensitive to cytosolic DNA, typically observed in tumor cells." (PMID 36902456, 2023). "cGAS can be activated by any dsDNA in a sequence independent manner to activate cGAS-STING signaling pathway, which has been reported to be a critical pathway for anti-tumor, antiviral and anti-bacterial defense." (PMID 36926351, 2023). "Meanwhile, due to the ability of Mn2+ to amplify cGAS‐STING activation, CMP showed better anti‐tumor immunity." (PMID 37933288, 2023). "Emerging evidence supports context-dependent pro-tumorigenic effects of cGAS–STING signalling, both on a cell-intrinsic and tumour microenvironment level." (PMID 36876871, 2023). "Cascade tumor pyroptosis and cyclic GMP‐AMP synthase‐stimulator of interferon genes (cGAS‐STING) immunotherapy at tumor sites by hMnO2@HA@NMA (MHN) nanogenerators (NGs)." (PMID 37400368, 2023). "The cGAS‐STING pathway, as a vital innate immune signaling pathway, has attracted considerable attention in tumor immunotherapy research." (PMID 37807827, 2023).
tumor (continued). "The mice were intraperitoneally injected with a cGAS-STING inhibitor (RU.521, 5 mg/kg) or normal saline every 5 days after assessment of the tumour volume." (PMID 37667220, 2023). "The present article discusses tumor-supportive changes occurring in the tumor microenvironment (TME) or tumor immune microenvironment (TIME) MICs, specifically emphasizing cGAS/STING signaling-dependent alteration." (PMID 37380989, 2023). "Collectively, our results demonstrated that macrophage PP2Ac deletion reduced tumor growth in a cGAS-STING dependent manner and synergized with STING-activating treatments including cGAMP, radiation, and anti-PD1 blockade in multiple syngeneic tumor models." (PMID 36757811, 2023). "A value of IHC signal ≧3 was considered as the presence of the expression of cGAS and STING in tumor cells in CRC." (PMID 37345163, 2023). "cGAMP stimulated DC to create IFN-β via the cGAS-STING-IRF3 pathway and IFN-β then cross-primed tumour-specific CD8+ T cells." (PMID 37162544, 2023). "The cGAS/STING pathway can promote the secretion of type I-interferon (IFN) and the production of pro-inflammatory cytokines to increase tumor infiltration of antitumor T cells." (PMID 37532731, 2023). "Activation of the cGAS-STING pathway as immunotherapy has shown promising results, including long-term remissions in some preclinical tumor models." (PMID 37655095, 2023). "The combined system achieved enhanced tumor synergistic immunotherapy through TME reprogramming via the peroxidase-like activity of the CoNCDs and cGAS–STING signaling pathway agonist synergistically." (PMID 37762239, 2023). "The inherent DNA instability in tumour cells can stimulate their intrinsic cGAS (cyclic GMP‐AMP synthase) to generate cGAMP, thereby activating the immune response and ultimately resulting in the elimination or clearance of the tumour cells." (PMID 37488750, 2023). "DNA‐PK cooperates with cGAS‐STING signalling to regulate type I Interferons, chemokines and tumor‐related inflammatory responses." (PMID 36574362, 2023). "The cGAS‐STING pathway has been identified as an important pathway for activating immune cells and is widely used in tumor immunotherapy." (PMID 37933288, 2023). "In CC TIME, tumor-derived exosomes with TGF-β, cGAS, and 2′-3′-cGAMP activate STING signaling in tumor-infiltrated T cells to promote induced-Treg (iTreg) expansion." (PMID 37508372, 2023). "Later on, cascade tumor pyroptosis and cyclic GMP‐AMP synthase‐stimulator of interferon genes (cGAS‐STING)‐based immunotherapy is achieved and tumor growth is effectively inhibited." (PMID 37400368, 2023). "This action of TREX1 inhibits the cGAS-STING-mediated expression of type I IFNs, in turn attenuating the cytotoxic effects of CD8+ T cells on tumor cells." (PMID 37920470, 2023). "In this design, the CRISPR plasmid enhances activation of the cGAS/STING pathway and reverses exhaustion of T cells, by affecting methionine metabolism in tumor cells." (PMID 37532731, 2023). "After RT, the DNA damage is signalized through cGAS-STING, leading to the activation of CD8+ cytotoxic T cell-mediated tumor destruction." (PMID 37511215, 2023). "Here, the authors present an optogenetic system that regulates the cGAS/STING pathway remotely and demonstrate its efficacy in murine tumour models." (PMID 37673917, 2023). "The cGAS–STING pathway plays an indispensable role in radiotherapy, chemotherapy, and anti-tumor immune checkpoint therapy." (PMID 37686127, 2023). "The STING agonist 2′,3′-cGAMP has been shown to activate the cGAS-STING-IRF3 pathway and modify the tumor immune microenvironment in the treatment of solid tumors (triple-negative breast cancer (TNBC) cells)." (PMID 37354378, 2023). "This inverse correlation between the expression of cGAS and STING in cancer cells was also observed within spatially heterogeneous tumours." (PMID 37612508, 2023).
tumor (continued). "cGAS/STING signaling and IFN-1 expression in tumor cells after hypofractionated IR exposure have been associated with sustained immunogenic locoregional and distant (abscopal) antitumor responses in the context of an immune checkpoint blockade." (PMID 37834346, 2023). "Released mtDNA, cGAMP, and bacteria activate the cGAS/STING pathway in immune cells, triggering the activation of both innate and adaptive immunity, resulting in enhanced anti-tumor efficacy." (PMID 37354378, 2023). "Further investigation indicated that TZM-mediated radio-/radiodynamic therapy with tumor ICD promoted DC maturation and up-regulated PD-L1 expression through the cGAS-STING pathway with antitumor immune response amplification." (PMID 37766117, 2023). "The cGAS-STING pathway, central to this interaction, is a key innate immunity component that responds to cytosolic DNA, including tumor-derived DNA, triggering inflammatory responses and antitumor immunity through the production of IFN-1 and other cytokines." (PMID 38111536, 2023). "As STING agonist, Mn2+ can up-regulate antigen-presenting cells’ ability to present tumor antigens through cGAS-STING, and promote tumor tissue invasion and specific killing ability of CD8+T cells." (PMID 37920470, 2023). "cGAS-STING signalling plays an important regulatory role in microbial and tumour immunology through the induction of cytokines, mainly type I interferons." (PMID 37537600, 2023). "2′,3′-cGAMP activated the cGAS–STING pathway and induced the activation of the autoimmune system, resulting in a systemic anti-tumor effect." (PMID 37762239, 2023). "This has been shown using different models of tumors where the cancer cells need to express cGAS and the host cells only need to express STING to initiate responses leading to tumor rejection." (PMID 37287967, 2023). "Some reports suggest that bacterial DNA can activate the cGAS-STING pathway and upregulate type I interferon, which is a key cytokine for innate and adaptive immunity, resulting in an adjuvant anti-tumor immune response." (PMID 36798129, 2023). "The cyclic GMP-AMP synthase (cGAS)/interferon gene stimulator (STING) pathway, a key part of innate immunity, has lately been exploited as a progressive candidate for augmenting tumor therapy." (PMID 37575228, 2023). "The cGAS-STING pathway is a vital regulator of the innate immune response during viral infections, inflammation, and anti-tumor immunity." (PMID 37051596, 2023). "Among the contributing mechanisms, lowering cholesterol levels in the tumor microenvironment may promote antigen presentation and T cell effector function, while reduced protein prenylation may impact DNA repair, and the resulting accumulation of cytosolic DNA may drive cGAS/STING signaling." (PMID 37568764, 2023). "Of these, the function of the cyclic GMP–AMP synthase (cGAS)-stimulator of interferon genes (STING) pathway, which contains telomere-related molecules, is a well-known contributor to the tumor microenvironment (TME)." (PMID 35741087, 2022). "In contrast, our results show that inhibition of the cGAS-STING axis in serum-depleted condition results in cell death and tumor growth suppression." (PMID 35992877, 2022). "The cGAS-STING pathway has been found to be involved in many disease processes, such as immune defense, tumor progression, autoimmune diseases, and neuron degeneration." (PMID 36230972, 2022). "The increased activation of the cGAS/STING pathway resulted in the production of IL-15, increased activation of NK and CD8+ T cells, and an increased level of tumor cell necrosis." (PMID 36059473, 2022). "In this work, we specifically investigate the interaction between the cGAS-STING pathway, tumor inflammation, CIN, TMB, and response to immunotherapy." (PMID 36923311, 2022). "STING agonists can activate the cGAS-STING pathway, induce the expression of type I IFN, improve the tumor environment, and lead to promoted anti-tumor effects." (PMID 35889509, 2022).